NCOR1 (nuclear receptor corepressor 1)
Diseases named in the same sentence as NCOR1 in open-access papers (continued):
Sharing a sentence is not in itself a finding about the gene and the disease.
colon cancer (5 papers, 2011 to 2026). "Thus, NCOR1 plays a novel role in preventing cancer-associated senescence and could represent a target for controlling colon cancer progression." (PMID 34503224, 2021). "APC, SMAD4, NF1 (neurofibromin 1), ARID5B, NCOR1 (nuclear receptor corepressor 1), IGFR1R (insulin like growth factor 1 receptor) and GNAS (GNAS complex locus) were the most often mutated genes in patient-derived colon cancer cells." (PMID 33050525, 2020). "APC, SMAD4 (SMAD family member 4), NF1 (neurofibromin 1), ARID5B, NCOR1 (nuclear receptor co-repressor 1), IGFR1R (insulin like growth factor 1 receptor) and GNAS (GNAS complex locus) were the most often mutated genes in patient-derived colon cancer cells, YUMC-C1 and YUMC-C2." (PMID 33050525, 2020). "However, it is unclear whether NCOR1 is functionally involved in colon cancer." (PMID 34503224, 2021). "RNA-seq transcriptome profiling of colon cancer cells confirmed the senescence phenotype in the absence of NCOR1 and predicted the occurrence of a pro-migration cellular signature in this context." (PMID 34503224, 2021). "The acquisition of a pro-metastasis signature in the absence of NCOR1 could indicate long-term potential adverse consequences of colon-cancer-induced senescence." (PMID 34503224, 2021).
glioblastoma (5 papers, 2017 to 2023). The most malignant astrocytic tumor (WHO grade IV). "NCoR1 degradation by CMA also influences the unfolded protein response and apoptosis in glioblastoma, indicating that CMA inhibition is also involved in cancer development." (PMID 37524243, 2023).
osteosarcoma (5 papers, 2012 to 2024). A usually aggressive malignant bone-forming mesenchymal neoplasm, predominantly affecting adolescents and young adults. "The high proportion of NCOR1 and VEGFA amplification may be a special molecular feature of Chinese osteosarcoma patients." (PMID 35756627, 2022).
steatosis (5 papers, 2019 to 2025). Increased lipid within the cytoplasm of cells. "Indeed, when NCoR1 or HDAC3 is specifically deleted in hepatocytes a lipogenic program is activated leading to steatosis without evidence of insulin resistance or glucose intolerance." (PMID 31404087, 2019).
thyroid cancer (5 papers, 2013 to 2022). "Further analysis of NCOR1 variants in an expanded cohort and functional analysis will help define its role in the pathogenesis of thyroid cancer." (PMID 34680332, 2021). "Given the fact of NCOR1 as AR suppressor in PCa progression and an oncogenic role in thyroid cancer, it is reasonable for NCOR1 to act as both oncogene and tumor suppressor." (PMID 33058520, 2020). "The present study elucidated the in vivo actions of NCOR1 in carcinogenesis using a mouse model (ThrbPV/PV mice) that spontaneously develops thyroid cancer." (PMID 23840792, 2013). "Whether NCOR1 also play a role in the pathogenesis of other thyroid cancer subtypes needs further investigation." (PMID 34680332, 2021). "Some studies provided direct evidence in vivo that NCOR1 could function as an oncogene via transcription regulation in a mouse model of thyroid cancer." (PMID 33058520, 2020). "The present studies provided direct evidence in vivo that NCOR1 could function as an oncogene via transcription regulation in a mouse model of thyroid cancer." (PMID 23840792, 2013). "Among the genes previously implicated in thyroid cancer, LRP1B (LDL Receptor Related Protein 1B) was found mutated in FTC and FVPTC negative cases (cases 27 and 8) and NCOR1 (Nuclear Receptor Corepressor 1) in 2 HCC negative cases (cases 28 and 30)." (PMID 34680332, 2021).
cervical cancer (4 papers, 2021 to 2025). A primary or metastatic malignant neoplasm involving the cervix. "Co-IP data also confirmed that OCT4 indeed interacted with NCOR1 in the cervical cancer cell line SiHa." (PMID 35875100, 2022).
Insulin resistance (4 papers, 2016 to 2024). Increased resistance towards insulin, that is, diminished effectiveness of insulin in reducing blood glucose levels. "Compared with the WT mice, glucose intolerance, insulin resistance and hyperinsulinemia were all greatly improved in the IKO mice, indicating that NCoR1 deficiency in IECs results in an insulin-sensitive phenotype." (PMID 39807334, 2024). "After injection, the induced deletion of NCoR1 in IECs prevented weight gain in NCoR1ΔIECi mice and improved insulin resistance and glucose tolerance compared to NCoR1f/f mice." (PMID 39807334, 2024). "Similarly, genetic deletion of NCoR1 has improved insulin resistance and reduced adiposity in mouse models." (PMID 37674539, 2023). "Increased HDAC3 or NCoR1 activity could limit lipolysis, resulting in a reduction in the breakdown of stored triglycerides and perhaps contributing to insulin resistance." (PMID 37674539, 2023).
liver cancer (4 papers, 2019 to 2024). An epithelial or non-epithelial malignant neoplasm that arises from the liver. "Notably, we observed that the frequently mutated gene NCOR1 exhibited upregulated regulon activities in stem-like cells from both cirrhosis and liver cancer." (PMID 38645221, 2024). "In summary, this unexpected but unbiased finding reinforces the association between NCOR1/2 and JUN’s capacity to suppress YAP target genes and demonstrates a role in YAP-dependent liver cancer." (PMID 39210147, 2024). "Therefore, resistance of the liver-specific Atg7-knockout mice to progress from benign adenoma to liver cancer might be due to persistent expression of NCoR1." (PMID 31879337, 2020).
lung carcinoma (4 papers, 2011 to 2023). "To explore the option that NCOR1 also have a role in other cancer types, we explored if mutations at this gene were linked with detrimental prognosis in lung cancer." (PMID 30485330, 2018). "The down-regulation of NCOR1 was associated with prognosis in patients with lung cancer." (PMID 31661545, 2019). "Previous study found that NCoR1 contains a KFERQ-like motif and that CMA contributes to the elimination of misfolded NCoR1 in lung cancer cells." (PMID 37524243, 2023). "Multivariate cox regression analysis revealed that NCOR1 was an independent prognosis factor for lung cancer." (PMID 31661545, 2019). "There are few reports on NCOR1 in lung cancer study, therefore we performed an IHC assay in NSCLC tissue microarrays." (PMID 31661545, 2019).
metabolic syndrome (4 papers, 2015 to 2024). A cluster of metabolic risk factors for CARDIOVASCULAR DISEASES and TYPE 2 DIABETES MELLITUS. "Our study showed that intestinal NCoR1 deficiency didn't affect appetite but showed a robust effect on metabolic syndrome by regulating both energy expenditure and lipid intake." (PMID 39807334, 2024). "By focusing on NCOR1 these analyses are given further relevance as this protein has emerged as a major disease driver in a range of cancers and is implicated in metabolic syndromes." (PMID 26117541, 2015). "In this study, we found that the deletion of NCoR1 in intestinal epithelial cells (IECs) mainly activated the nuclear receptor PPARα and attenuated metabolic syndrome by stimulating thermogenesis." (PMID 39807334, 2024). "Therefore, the simultaneous regulatory effect of intestinal NCoR1 on both lipid intake and energy expenditure strongly suggests that it is a promising target for developing metabolic syndrome treatment." (PMID 39807334, 2024). "To assess whether intestinal NCoR1 could regulate metabolic syndrome, we generated conditional IEC NCoR1-knockout (IKO) mice utilizing the Cre-LoxP method." (PMID 39807334, 2024).
non-small cell lung carcinoma (4 papers, 2019 to 2023). A group of at least three distinct histological types of lung cancer, including non-small cell squamous cell carcinoma, adenocarcinoma, and large cell carcinoma. "Misfolded NCoR1 has been found in primary human cancer tissues derived from non-small cell lung cancer, and CMA-mediated degradation of misfolded NCoR1 promotes tumor cell survival by lowering ER stress." (PMID 37524243, 2023).
autism (3 papers, 2016 to 2023). Persistent deficits in social interaction and communication and interaction as well as a markedly restricted repertoire of activity and interest as well as repetitive patterns of behavior. "Furthermore, with specific relevance to the recent discovery of NCOA7 mutations in autism, several de novo genetic variants in the nuclear receptor corepressors NCOR1 and NCOR2 are found in pediatric patients with intellectual disabilities or ASD." (PMID 33340069, 2021).
B-cell lymphoma (3 papers, 2022 to 2024). "Furthermore, BCL6 interactions with co-repressor proteins BCOR and NCOR1/2, which were differentially expressed in our dataset, represent another key regulator of GC B cell function that is dysregulated in B cell lymphomas." (PMID 36619973, 2023).
chronic myeloid leukemia (3 papers, 2015 to 2022). "ENCODE undertook ChIP-Seq toward NCOR1 in K562 cells, which are a chronic myelogenous leukemia (CML) cell line, that resemble erythrocyte precursors." (PMID 26117541, 2015). "Mining public microarray data revealed that NCOR1-targeted genes were significantly enriched in Imatinib response gene signatures in cell lines and chronic myelogenous leukemia (CML) patients." (PMID 26117541, 2015).
colitis (3 papers, 2020 to 2024). Inflammation of the colon. "Since both T cell subsets are linked with the development of colitis, it is likely that the reduction of these subsets is one of the contributing factors preventing T cell-mediated pathology by NCOR1-deficient CD4+ T cells." (PMID 32318068, 2020). "In vivo, effector functions were compromised since adoptive transfer of NCOR1-deficient CD4+ T cells resulted in attenuated colitis due to lower frequencies of IFNγ+ and IFNγ+IL-17A+ Th cells and overall reduced CD4+ T cell numbers." (PMID 32318068, 2020). "In contrast, upon adoptive transfer and induction of colitis the subset distribution of NCOR1-deficient CD4+ T cells is changed and hence the percentage of IFNγ+ Th cells might be reduced." (PMID 32318068, 2020). "Since it has been shown that Treg cells home to mLNs early after transfer and proliferate there until colon inflammation is resolved, one might speculate that the failure of NCOR1-cKO Treg cells to prevent colitis is caused by the reduction in Treg numbers in gut-draining LNs." (PMID 39466314, 2024). "NCOR1 controls immunometabolic functions in several tissues and has been recently shown to protect against experimental colitis in mice." (PMID 34503224, 2021). "Some evidence supports a role for NCOR1 in neonatal intestinal epithelium maturation and the maintenance of epithelial integrity during experimental colitis in mice." (PMID 34503224, 2021). "Of note, the diminished population of IFNγ-expressing cells in the adoptive transfer colitis model was an unexpected observation, since we observed that activated NCOR1 cKOCd4 CD4+ T cells produced enhanced levels of IFNγ." (PMID 32318068, 2020). "A key role for NCOR1 in regulating Th effector functions was further identified in vivo in an adoptive CD4+ T cell transfer model of colitis." (PMID 32318068, 2020). "Due to reduced numbers of peripheral T cells in NCOR1 cKOCd4 mice, we employed an adoptive CD4+ T cell transfer model of colitis to start with comparable numbers of WT and NCOR1 cKOCd4 CD4+ T cells." (PMID 32318068, 2020). "NCOR1 is essential for Treg cell-mediated protection in adoptive CD4+ T cell transfer colitis." (PMID 39466314, 2024). "In addition, we employed an adoptive transfer model of colitis to study the impact of NCOR1 deletion during CD4+ T cell-mediated autoinflammation." (PMID 32318068, 2020). "Similar frequencies and numbers of wild-type (WT) and NCOR1-cKO Treg cells within small intestinal intraepithelial lymphocyte (SI-IEL) and lamina propria cell (SI-LP) populations in adoptive CD4+ T cell transfer colitis." (PMID 39466314, 2024). "NCOR1-deficient Treg cells failed to protect mice from severe weight loss and intestinal inflammation associated with CD4+ T cell transfer colitis, indicating impaired suppressive function." (PMID 39466314, 2024). "In addition, in an adoptive CD4+ T cell transfer colitis model, co-transferred NCOR1-cKO Treg cells even failed to protect recipient mice from weight loss and intestinal tissue damage in comparison to co-transferred WT Treg cells." (PMID 39466314, 2024). "This suggests that lower numbers of NCOR1-deficient CD4+ T cells upon transfer might not be the primary cause for the absence of inflammation, although we cannot rule out that this, together with a disease-protective cytokine expression pattern, contributes to the attenuated colitis pathology." (PMID 32318068, 2020).
hepatocellular carcinoma (3 papers, 2019 to 2023). A malignant tumor that arises from hepatocytes. "Remarkably, decreased expression of NCoR1, focal deletion of 17p11.2 containing NCoR1 and mutations of NCoR1 have been specified in human hepatocellular carcinoma." (PMID 31879337, 2020). "We observe impaired ketogenesis and increases in PAK4 protein and NCoR1 phosphorylation levels in liver tissues of high fat diet-fed mice, NAFLD patients, and hepatocellular carcinoma patients." (PMID 37591884, 2023).
lung adenocarcinoma (3 papers, 2018 to 2023). A carcinoma that arises from the lung and is characterized by the presence of malignant glandular epithelial cells. "Previous studies have reported that NCOR1 is considered a tumor suppressor gene in lung adenocarcinoma, and its mutation is associated with poor prognosis of cancer, while high expression of NCOR1 is linked to better prognosis." (PMID 38030614, 2023). "The mutations in the NCOR1 were reported to be associated with the prognosis of hormone receptor negative breast and lung adenocarcinoma." (PMID 35756627, 2022). "In conclusion, hereby we describe the presence and prognostic role of mutations in the NCOR1 gene in hormone receptor negative breast and lung adenocarcinomas, and we also confirm that NCOR1 is a tumor suppressor gene." (PMID 30485330, 2018). "In conclusion, in the present work we describe the presence and prognostic role of mutations at NCOR1 gene in hormone receptor negative breast and lung adenocarcinomas and we also confirm that NCOR1 is a tumor suppressor gene." (PMID 30485330, 2018).
myocardial infarction (3 papers, 2023). Gross necrosis of the myocardium, as a result of interruption of the blood supply to the area, as in coronary thrombosis. "Furthermore, NCOR1 deficiency was found to inhibit proinflammatory factors released in the classical activation pathway of macrophages and to enhance the expression of M2-type anti-inflammatory genes in the context of myocardial infarction." (PMID 38030614, 2023). "Genetic deletion of NCoR1 in macrophages resulted in decreased infarct size and enhanced cardiac function in mice with experimental myocardial infarction, suggesting a critical role for NCoR1 in the heart." (PMID 37674539, 2023).
allergic disease (2 papers, 2017 to 2023). An immune response that occurs following re-exposure to an innocuous antigen, and that requires the presence of existing antibodies against that antigen. "However, NCOR1 has not been studied in allergic diseases such as asthma." (PMID 38030614, 2023).
anencephaly (2 papers, 2019 to 2020). A rare neural tube defect during pregnancy, resulting in the absence of a large portion of the brain and skull in the fetus. "However, whole genome sequencing techniques found candidate NTDs loci and genes in chromosomes 2, 7, 10 and 17 (some of which, i.e. WIPI1, SPHKAP and NCOR1, have recently been associated with anencephaly)." (PMID 32448340, 2020). "Missense variants in WIPI1 may play a role in the genetic etiology of anencephaly, and LoF variants in SPHKAP and NCOR1 may also contribute to anencephaly." (PMID 31849593, 2019). "A total of 13 DNVs were identified in 8 anencephaly trios by WES, including two loss of function (LoF) variants detected in pLI > 0.9 genes (SPHKAP, c.2629_2633del, and NCOR1, p.Y1907X)." (PMID 31849593, 2019).
heart failure (2 papers, 2020 to 2023). Inability of the heart to pump blood at an adequate rate to meet tissue metabolic requirements. "Overall, it has been shown that HDAC3 and NCoR1 are dysregulated in heart failure and is associated with adverse cardiac remodeling and dysfunction." (PMID 37674539, 2023). "Inhibition of HDAC3 and NCoR1 has been explored as a potential therapeutic strategy to mitigate cardiac remodeling and improve cardiac function in heart failure." (PMID 37674539, 2023). "Taken together, these results suggest that selective modulation of NCOR1 in macrophages could have important implications for the prevention of myocardial ischemic damage, heart failure, coronary heart disease and intracoronary stent restenosis." (PMID 33117357, 2020). "Hence, macrophage NCOR1 may act as an upstream regulator of myocardial inflammation thus participating to left ventricular hypertrophy, diastolic dysfunction and microvascular disease, key hallmarks of heart failure." (PMID 33117357, 2020).
hypertrophic cardiomyopathy (2 papers, 2019). A condition in which the myocardium is hypertrophied without an obvious cause. "NCoR1 upregulation during pathological overload and hypertrophic cardiomyopathy is likely a compensatory mechanism to prevent cardiac over‐growth." (PMID 31622030, 2019). "Western blotting analysis revealed that the protein level of NCoR1 was elevated in heart samples from hypertrophic cardiomyopathy patients (Fig EV1B and C)." (PMID 31532577, 2019).
hypothyroidism (2 papers, 2017 to 2021). Abnormally low levels of thyroid hormone. "NCoR1 was enriched to the R1 in hypothyroidism when TSHβ gene transcription was increased and enriched to R2 in hyperthyroidism for repression of TSHβ gene transcription." (PMID 34237030, 2021). "The present studies showing that TRα1 mutants caused erythroid disorders further expanded the scope of the RTHα-resistant target tissues regulated by NCOR1 and further strengthened the conclusion that aberrant recruitment of NCOR1 by TRα1 mutants leads to clinical hypothyroidism in patients." (PMID 29273766, 2017).
virus infection (2 papers, 2008 to 2022). "Studies in macrophage have shown that NCoR1 depletion leads to increased fatty acid oxidation through derepression of LXR and also increased fatty acid oxidation pathway is known to have a role in limiting virus infection in DCs through Sirt1." (PMID 35849243, 2022).